CTLA4 (cytotoxic T-lymphocyte associated protein 4)
Diseases named in the same sentence as CTLA4 in open-access papers (continued):
Sharing a sentence is not in itself a finding about the gene and the disease.
cancer (continued). "Additionally, CAFs upregulate ligands for programmed death receptor 1 (PD-1) and cytotoxic T lymphocyte-associated antigen 4 (CTLA-4), inducing apoptosis of effector T lymphocytes and aiding cancer cells in immune evasion." (PMID 39744013, 2024). "Furthermore, using antibodies to control the CTLA-4/CD28 pathway is envisaged to treat cancers and autoimmune diseases." (PMID 38191571, 2024). "CTLA-4 upregulation has been described as a mechanism for immune-evasion of cancer cells." (PMID 38254772, 2024). "PD-1 and CTLA-4 are expressed by activated T cells and most studies of these signaling pathways have focused on their influence on effector responses, which form the basis for checkpoint blockade in cancer." (PMID 39795946, 2024). "The first successful pathway involved the programmed death 1 (PD-1)/programmed death ligand 1 (PD-L1) and cytotoxic T lymphocyte-associated protein 4 (CTLA-4) pathways, which are key mediators through which cancer cells evade antitumor T-cell-mediated cytotoxicity." (PMID 38903506, 2024). "However, despite the undeniable success of anti-PD-1, PD-L1, and CTLA-4 antibody treatments, their effectiveness is limited either by certain types of malignancies or by the arising problem of cancer resistance." (PMID 39061159, 2024). "This distribution reflects the current trends in immunotherapy treatments for cancer, particularly the widespread use of pembrolizumab and nivolumab compared to that of ipilimumab (anti-CTLA-4) due to their side-effect profiles and their proven efficacy for treatment of various types of cancer." (PMID 39201062, 2024). "In the case of anti-CTLA-4, the initial immune response may be enhanced; this may prompt the immune system to attack cancer cells earlier and potentially lead to long-term efficacy." (PMID 38756774, 2024). "It appears that mice with some cancer models may have better response with anti‐CTLA‐4 antibody than anti‐PD‐1 antibody contrary to the observation in human cancers." (PMID 38686626, 2024). "Combined CTLA-4 and PD-1 blockade has increased anti-cancer efficacy, but it may also result in heightened toxicity." (PMID 38375475, 2024). "CTLA-4 is upregulated in various cancers, including CRC, to promote disease progression." (PMID 38313367, 2024). "Thus, it is conceivable that GPER promotes the expression of PD-1 and CTLA-4 in Tregs derived from patients with breast cancer, thereby supporting the advancement of cancer." (PMID 38476263, 2024). "Ipilimumab is an anti-CTLA4 antibody approved by the FDA for treating other types of cancer." (PMID 39409094, 2024). "Therefore, they are prognostic factors for anti‐CTLA‐4 medication and result in reduction of cancers in mice model." (PMID 38571678, 2024). "Although the development of autoimmune bullous diseases in cancer patients treated with ICIs is less likely to occur, the risk of the occurrence of bullous eruption in cancer patients treated with either PD-1 or PD-L1 inhibitors was higher than noted in cancer patients treated with CTLA-4 inhibitor." (PMID 39795946, 2024). "Recent research highlighting anti-CTLA-4 combination strategies, such as Treg cell depletion, utilization of cancer vaccines, and consideration of the gut microbiome, has revealed promising preclinical results that are poised for subsequent investigation in patients." (PMID 38956700, 2024). "Aberrant expression of PD-1 and CTLA-4 has been observed in several types of cancer." (PMID 38672574, 2024). "The combined application of PD-1 and CTLA-4 antibodies was initiated at an early stage and has been widely used in clinical practice with a profound lasting response rate and controllable AEs, which has significantly changed the treatment of advanced cancer." (PMID 38581716, 2024). "Several hypotheses have been proposed to explain the mechanisms of anti-CTLA-4 immunotherapy in cancer." (PMID 38053333, 2024). "Ipilimumab was the first anti-CTLA4 ICI approved by FDA for the treatment of MSI-H cancers in 2018." (PMID 38254772, 2024).
cancer (continued). "This study suggests that systemic short-chain fatty acids, especially butyrate and propionate, may act as regulators, diminishing the anticancer effects of CTLA-4 inhibition in cancer patients." (PMID 39351241, 2024). "Blocking the cytotoxic T lymphocyte-associated protein 4 (CTLA-4)–programmed cell death protein 1 (PD-1)–programmed cell death ligand 1 (PD-L1) inhibitory pathway has enabled remarkable clinical responses and revolutionized the treatments of different cancers." (PMID 38349393, 2024). "To date, immune checkpoint inhibitors (ICI) have been designed to be able to act against CTLA-4/B7 and PD-1/PD-L1pathways, and the efficacy of combined immunotherapy with MoAb in cancer treatment has recently been applied, showing higher clinical efficacy compared to either agent individually." (PMID 38612483, 2024). "An additional 274 cancer patients were identified and were treated with anti-CTLA4 monotherapy." (PMID 38531883, 2024). "ICIs, particularly anti-programmed death-1 (PD-1)/programmed death-ligand 1 (PD-L1) and anti-cytotoxic T-lymphocyte-associated antigen 4 (CTLA-4) antibodies, which activate CD8-positive T cells and induce cancer cell mortality, have revolutionized the treatment of advanced cancers." (PMID 38887234, 2024). "Furthermore, T cells display a protein called PD‐1, which functions analogous to CTLA‐4 in ending a T cell response by adhering to PD‐L1 or PD‐L2 of additional cells like cancer cells." (PMID 38571678, 2024). "A pan-cancer analysis of associations between PSME2 and immune-related genes was also conducted, and TISMO was used to compare the expression of PSME2 between cancer cell lines treated in vitro with cytokines and in samples before and after in vivo anti-PD-1 and anti-CTLA4 treatment." (PMID 38385075, 2024). "However, to comprehensively understand the co-evolution of the immune system during cancer progression, we included several cell characterization markers, such as immune checkpoint inhibitors CTLA-4, PD-1, and PD-L1." (PMID 39481389, 2024). "This aptamer activated T cells by impeding the CTLA-4 interaction with B7-1/B7-2, enhancing the eradication of cancer cells, and augmenting NK cells’ capacity for detecting and eliminating HLA-E-expressing cancer cells by inhibiting NKG2A." (PMID 38473398, 2024). "Most of these anti-cancer targets cover PD-1, PD-L1, CTLA4, HER2, EGFR, and BCMA." (PMID 38254860, 2024). "Indeed, VISTA, PD-1/PD-L1, and CTLA-4 play different roles at different stages of the cancer–immunity cycle, suggesting a rationale for the combination of immunomodulators." (PMID 38503143, 2024). "Similarly, one systematic review showed that grade 3–4 immune-related adverse events (irAEs) were more prevalent with CTLA-4 inhibitors than with PD-1 inhibitors (31% versus 10%) for cancer treatment." (PMID 38319920, 2024). "The results suggest that CTLA-4 expression is associated with adverse prognostic factors in the IPS for advanced-stage CHL, supporting the notion that immune checkpoints play a role in cancer progression." (PMID 38978137, 2024). "We advise that combining RT with PD-1 and/or CTLA-4 blockade may be counterproductive in lymphocyte-depleted cancers, since these interventions drive Treg responses in this context." (PMID 38349740, 2024). "CTLA-4 is a critical immune checkpoint and target for cancer therapy." (PMID 39062076, 2024). "Additionally, CTLA-4, another inhibitory immune checkpoint expressed on activated T cells, serves as an effective target for cancer therapy." (PMID 39926600, 2024). "PD-L1, PD1, and CTLA4 suppress T-cell function and help cancer cells escape immunosurveillance." (PMID 39594778, 2024). "In particular, ICIs targeting CTLA4 and PD-1, two most clinically relevant immune checkpoints, and T-cell checkpoint inhibitors have fundamentally changed the treatment landscape of many cancers." (PMID 38713284, 2024).
cancer (continued). "Recently, abnormal expression of the CTLA-4 gene has been documented in many types of cancers, suggesting that it may contribute to the development and progression of cancer." (PMID 39464701, 2024). "Therapy targeting the CTLA-4 pathway has been implemented in the field of immunotherapy and may be synergistically combined with PD-1 inhibitory therapy for specific cancer types." (PMID 39372415, 2024). "Furthermore, RBFOX2 expression showed a significant association with immunosuppressive genes like PD-L1, CTLA4, VTCN1, KDR, and TGFBR1 across different types of cancers." (PMID 38881877, 2024). "Inhibition or blockade of CTLA-4 and PD-1 checkpoints dramatically impacts cancer therapy." (PMID 38791338, 2024). "The effectiveness of these blockades is seen only with PD-1+ and CTLA-4+ cancer patients." (PMID 38785930, 2024). "Cancer immunotherapy has seen significant advancements through the targeted inhibition of specific immune checkpoints, particularly cytotoxic T lymphocyte antigen-4 (CTLA-4) and PD-1/PD-L1." (PMID 40808797, 2024). "Therefore, the functions of CTLA-4 need to be carefully considered in the TME when targeting CTLA-4 in cancer therapy." (PMID 38927907, 2024). "Notably, in the case of cancer, the administration of antibodies targeting CTLA-4, followed by antibodies targeting PD-1 or a combination of both, has demonstrated effectiveness in reducing tumor growth." (PMID 38813058, 2024). "However, the correlation between CTLA-4 expression and patient prognosis in different cancers is controversial." (PMID 38763973, 2024). "Notably, VISTA is highly connected to CTLA-4, suggesting their involvement in the destruction of cancer cells by T cells." (PMID 38357542, 2024). "For example, enhanced immunotherapies such as cancer vaccines or CTLA-4 immune checkpoint inhibitors might be more effective for SL-CRC." (PMID 39619673, 2024). "Thus, various methods of immunotherapy were developed such as ICIs including PD-L1 or CTLA-4, monoclonal antibodies, and adaptive cell therapies aiming to strengthen the immune system in recognizing and obliterating cancer." (PMID 38397971, 2024). "To determine whether the antitumor effects of the anti-CTLA-4 Ab depends on direct MHC-mediated recognition of cancer cells by T cells, we generated Hepa1-6 #12 cells with beta-2 microglobulin (β2m) or MHC-II expression KO using the CRISPR-Cas9 technique." (PMID 39106430, 2024). "The US Food and Drug Administration (FDA) has approved three distinct categories of ICIs for treating various cancer types: CTLA-4 inhibitors (Ipilimumab), PD-L1 inhibitors (such as Atezolimumab, Avelumab, and Durvalumab), and PD-1 inhibitors (including Pembrolizumab, Nivolumab, and Cemiplimab)." (PMID 38893120, 2024). "Current immunotherapy methods aim to enhance immune function against tumor cells, utilizing diverse approaches such as blocking PD-1, PD-L1, and CTLA4, using cancer vaccines, or administering engineered immune cells, such as natural killer (NK) cells or CAR T cells." (PMID 39367418, 2024). "Although very few anti-CTLA-4 clinical studies have been performed in patients with BC, this may change with a deeper understanding of CTLA-4 function in cancer immunity." (PMID 38956700, 2024). "With its approval in 2011, the anti-cytotoxic T lymphocyte antigen 4 (CTLA-4) antibody ipilimumab started a new era of cancer treatment, as immune checkpoint inhibitors (ICIs) that primarily block programmed death 1 (PD-1) as well as CTLA-4 became the cornerstone of immunotherapy." (PMID 38898505, 2024).
cancer (continued). "Immune checkpoint inhibitor (ICI) therapies, particularly PD-1 blockade and anti-CTLA-4 treatments, have changed the treatment landscape of virous cancers, showing great potential in the treatment of different cancer patients, but sensitivity to these therapies is limited to certain individuals." (PMID 39372415, 2024). "Specifically, PD-1, PD-L1, and CTLA-4 are commonly employed in cancer immunotherapy." (PMID 39126025, 2024). "In addition, such ICBs are efficient for use with the subset of cancer patients who are CTLA-4-positive and PD-1-positive." (PMID 38785930, 2024). "At present, several ICIs have been approved by the FDA for the clinical treatment of various cancers, including nivolumab and pembrolizumab for blocking PD-1, atezolizumab and avelumab for blocking PD-L1, and ipilimumab and tremelimumab for blocking CTLA-4 on the cell surface." (PMID 38791528, 2024). "Besides the canonical immune checkpoints PD-1 and CTLA-4, alternative negative regulatory checkpoints have been found and are focused on by cancer biologists, clinical oncologists, and industry." (PMID 38773064, 2024). "Drugs that focus on PD-L1 and CTLA-4 are becoming more crucial in cancer therapy." (PMID 39726587, 2024). "Immune checkpoint inhibitors [e.g., programmed cell death protein 1/programmed death-ligand 1 (PD-1/PD-L1) and cytotoxic T-lymphocyte-associated antigen 4 (CTLA-4)] and chimeric antigen receptor (CAR)-T-cell therapies have made significant progress in extending cancer patients’ lives." (PMID 38405432, 2024). "The use of treatments, such as programmed death protein 1 (PD1) or cytotoxic T lymphocyte-associated antigen 4 (CTLA-4) antibodies, that loosen the natural checks upon immune cell activity to enhance cancer killing have shifted clinical practice and outcomes for the better." (PMID 37217603, 2023). "In addition, we also revealed that the Writer-Score was negatively related to the expression of PD-1, PD-L1, LAG-3 and CTLA-4 in majority of cancers." (PMID 37638051, 2023). "While chemotherapy, radiotherapy, and surgery have long been considered the basis of cancer treatment, the first successful FDA-approved ICB drug in 2011—the anti-CTLA-4 monoclonal antibody ipilimumab —revolutionized immunotherapy as a new pillar of cancer therapy." (PMID 36826125, 2023). "In case of cancer immunotherapy, the use of monoclonal antibodies of CTLA-4 could increase T cell proliferation and their cytokine production." (PMID 36109471, 2023). "More importantly, there was also a remarkably positive correlation between SLC2A1 and PD-L1 or CTLA4 across cancers, which could reflect its prognosis and immunotherapy significance." (PMID 37833332, 2023). "In addition to combining OMV-based ISV with cancer vaccines, other combinations should be tested, including in situ vaccination and checkpoint inhibitors (anti-CTLA4 and anti-PD1/PDL1 mAbs)." (PMID 37444437, 2023). "In many cancers, immunoregulatory mechanisms have been proved to hamper antitumor immunotherapy, including ligand-mediated engagement of IRs on effector cells, such as CTLA4, and induction of immunosuppressive cell subsets, such as Tregs or MDSCs." (PMID 37138869, 2023). "Studies have demonstrated that the CTLA-4/B7 and PD-1/PD-L1 axes regulate physiological immune homeostasis, downregulate inflammatory responses, and presumptively facilitate immune evasion of cancer cells." (PMID 36998469, 2023). "In a mice model, TNF inhibitors concomitantly with combined CTLA-4 and PD-1 immunotherapy ameliorated colitis and improved antitumor efficacy, which provided clinically feasible strategies to dissociate efficacy and toxicity for cancer immunotherapy." (PMID 36950013, 2023). "At the same time, we downloaded the IPS which could predict the response of the cancer patients to immunotherapy with anti-PD-1, anti-PD-L1 and/or anti-CTLA-4 treatment from TCIA." (PMID 37219794, 2023).
cancer (continued). "On the other hand, the discovery of immune checkpoint inhibitors, such as anti-PD-1 (programmed cell delath protein 1) and anti-CTLA-4 (cytotoxic T-lymphocyte-associated protein 4, CD152) antibodies, has shown improved patient outcomes for numerous cancers, including CRC." (PMID 37761948, 2023). "Therapies targeting CTLA-4 and PD-L1 promote T-cell-driven immune enhancement against cancer." (PMID 38139110, 2023). "Furthermore, it has been shown that the anti-CTLA-4 activity in cancer is constrained by short-chain fatty acids." (PMID 36677919, 2023). "Researchers are showing immense interest in cancer immunotherapy, specifically immunotherapy based on immune checkpoints such as programmed cell death 1 (PD-1), programmed death ligand 1 (PDL1), and cytotoxic T-lymphocyte-associated protein 4 (CTLA4)." (PMID 37174125, 2023). "In addition, other therapeutic factors showed synergistic effects to boost cancer IMT in combination with CTLA-4 blockades." (PMID 37735656, 2023). "With a glimpse at the recent advances of ICB, the combination paradigms between traditional cancer treatment modalities (e.g., radiotherapy, photodynamic therapy, photothermal therapy and sonodynamic therapy (SDT)) and PD-1/PD-L1 or CTLA-4 can improve the effects of cancer immunotherapy." (PMID 36759928, 2023). "CTLA-4 blockade has emerged as a promising immunotherapeutic approach in cancer treatment." (PMID 38201508, 2023). "Indeed, several antibodies specific to PD-L1 or CTLA-4 PD-1 have been recommended for the therapy of diverse cancers." (PMID 37419930, 2023). "Currently, there are many CTLA-4 inhibitors in a variety of modalities, including cell therapies, which are being developed in both preclinical and clinical stages to further harness the potential of the target for the treatment of certain types of cancer." (PMID 37110545, 2023). "The finding implies that in response to trastuzumab, expression of CTLA-4 in peripheral cells may be important in modulating patients' immune responses and cancer defenses." (PMID 38406785, 2023). "In the present study, undertook combination immunotherapy for RCC using an oral cancer vaccine (Bifidobacterium longum displaying WT1 tumor associated antigen (B. longum 420)) with anti-PD-1 and anti-CTLA-4 antibodies in a mouse syngeneic model of RCC to explore possible synergistic effects." (PMID 37340017, 2023). "The expression of PD-1 and CTLA-4 was synochronous in each composite score subgroups, which might indicate that combination of anti-CTLA-4 and anti-PD-1 therapy would increase the anti-cancer effects, especially in subgroup D." (PMID 36845378, 2023). "ICIs act upon T lymphocytes and antigen-presenting cells, versus programmed cell death protein 1 (PD1), programmed cell death protein ligand 1 (PD-L1), and cytotoxic T-lymphocyte antigen 4 (CTLA-4), deleting the immune tolerance of the T cells against cancer cells." (PMID 37190153, 2023). "Moreover, the expression of Cytotoxic T Lymphocyte antigen 4 (CTLA-4) is higher on CSCs compared to normal cancer cells." (PMID 37784157, 2023). "The first immune checkpoint to be clinically targeted for cancer treatment was CTLA-4." (PMID 38201559, 2023). "However, some studies using animal cancer models showed that, in addition to CTLA-4, PD-1/PD-L1 work as negative regulators in regional lymph nodes, which are the main sites for the induction of antitumor T cells." (PMID 37370399, 2023). "PD-1/PDL-1 and CTLA4 remain the most common and widely used targets for cancer immunotherapy." (PMID 38213548, 2023). "Thus, one of the strategies in designing cancer immunotherapies is to block the activation of CTLA4 and PD-1." (PMID 37205112, 2023). "By targeting PD1, PD-L1 and CTLA4, multidisciplinary treatments for cancer have improved." (PMID 37784135, 2023). "CTLA-4 is the most studied important checkpoint molecule in cancer progression." (PMID 38186404, 2023). "ICB therapy with PD1 and CTLA4 blockade is an effective treatment for certain cancers." (PMID 37686016, 2023).